PSEN1 (presenilin 1)
Diseases named in the same sentence as PSEN1 in open-access papers (continued):
Sharing a sentence is not in itself a finding about the gene and the disease.
cerebral amyloid angiopathy (14 papers, 2016 to 2025). "While carriers of PSEN1 mutations after codon 200 exhibit greater cerebral amyloid angiopathy and white matter hyperintensities, carriers of mutations before codon 200 exhibit a younger age of onset and greater amyloid burden." (PMID 38111006, 2023). "Familial AD mutations in APP and PSEN1 genes have been utilized to develop mouse models bearing Aβ pathologies including amyloid plaques and cerebral amyloid angiopathy." (PMID 30894120, 2019). "Previous pathological studies reported a particularly severe cerebral amyloid angiopathy (CAA) with post codon 200 PSEN1 mutations and amyloid beta coding domain APP mutations." (PMID 30090657, 2018). "A single intravenous injection of Aβ seeds derived from human AD brain extracts into amyloid precursor protein/presenilin 1(APP/PS1) mice resulted in cerebral amyloid angiopathy within 180 days after injection." (PMID 40077014, 2025). "Deletion of exon 9 in the human PSEN1 gene encoding for presenilin 1 (PSEN1 ΔE9) causes an early-onset form of AD characterized by the accumulation of amyloid plaques, neurofibrillary tangles, and cerebral amyloid angiopathy." (PMID 36552881, 2022). "Interestingly, Aβ was deposited as cerebral amyloid angiopathy (CAA) in large and small blood vessels within the brains of male and female APP/PSEN1 mice as well as Sorcs1 -/- x APP/PSEN1 mice." (PMID 26916443, 2016).
Down syndrome (13 papers, 2014 to 2025). "Age at onset spanned 36 years in families with the 3.4Mb APP duplication, 34 years in the APP V717I variant, 32 years in Down syndrome, 33 years in the E280A PSEN1 variant, and 29 years in the PSEN2 N141I variant." (PMID 35604690, 2022). "The CSF level of this 25-kDa CTF is higher in subjects with autosomal dominant AD linked to PSEN1 mutations, in demented Down syndrome individuals and in sporadic AD subjects compared to age-matched controls." (PMID 28559572, 2017). "In this study, 170 Down syndrome patients, groupedaccording to maternal meiotic stage of nondisjunction and maternal age at conception,and their parents were genotyped for PSEN-1 intron-8 andAPOE polymorphisms." (PMID 28767121, 2017). "Tau phosphorylation, however, was unchanged in neurons derived from patients with a PSEN1 mutation and a recent study demonstrated that the increase in tau phosphorylation observed in neurons derived from a patient with Down’s syndrome was unchanged following correction of the APP gene dosage." (PMID 30387070, 2018). "WMR has long been noticed to be roughly twice as common in AD as compared to normal elderly, and is reportedly pronounced relative to age-matched controls in subjects with PSEN1 and APP mutations and Down syndrome." (PMID 39656832, 2025). "Genetic familial effects beyond those associated with the E4 allele have been reported with APP gene dose (trisomy 21/Down syndrome; APP duplication) as well as mutations in PSEN1, PSEN2, and APP." (PMID 29497704, 2018). "Similar efforts are occurring in an extended Colombian family with a PSEN1 mutation, in APOE ε4 homozygotes, and in Down syndrome." (PMID 25217249, 2014). "Recent studies have identified some genetic predispositions (just as consanguineous marriage, maternal telomere length, maternal MCM9 polymorphisms, maternal Presenilin-1 and Apolipoprotein E polymorphisms) of women that may cause nondisjunction and Down syndrome birth at younger age." (PMID 36092906, 2022).
diabetes (10 papers, 2014 to 2025). "Concluding this paragraph, changes in Ca2+ homeostasis due to alterations in presenilin-1 function could be the missing link for the causative factors of diabetes and AD development and could shed some light into the correlation of these two diseases." (PMID 31817135, 2019). "Our results show that an 8-week treatment of TAN significantly reduced the FBG level, which is consistent with previous studies in rats with STZ-induced diabetes and amyloid precursor protein/presenilin 1 transgenic mice." (PMID 35899118, 2022). "The main risk factors include aging, genetics (presenilin 1 (PSEN1), PSEN2, and APP1 genes), hypertension, diabetes, hypercholesterolemia, stroke, obesity, sedentary lifestyle, depression, low socioeconomic status, and alcohol and tobacco use." (PMID 30405709, 2018). "In addition, studies have found that PSEN1 is also associated with T2DM, and this gene promotes Aβ deposition, which is a factor in the development of diabetes to AD." (PMID 37189611, 2023). "In STZ treated group (Diabetes control), the expression of BACE1, PSEN1, APAF1, CASPASE3, and CATALASE genes were upregulated in the cerebral cortex of the rat brain as compared to the untreated group (Vehicle control)." (PMID 33737876, 2020).
tauopathy (10 papers, 2017 to 2025). Neurodegenerative disorders involving deposition of abnormal tau protein isoforms (tau proteins) in neurons and glial cells in the brain. "Our study sheds light on the intricate regulatory roles of ApoE isoforms in modulating the Wnt signaling pathway, providing insights into potential mechanisms underlying the resistance to tauopathy observed in Patient α, the ApoE3Ch-carrying individual with the PSEN1 E280A mutation." (PMID 38571814, 2024). "Learning behavior and synaptic electrophysiological function were preserved at normal physiological levels even in the face of robust cerebral amyloidosis (in APP/PSEN1;Tyrobp−/− mice) or tauopathy (in MAPTP301S;Tyrobp−/− mice)." (PMID 36002854, 2022). "Mutations in genes encoding amyloid precursor protein (APP), presenilin 1 (PS1) and presenilin 2 (PS2) that promote amyloidosis and/or tauopathy are closely associated with the development of familial AD (FAD)." (PMID 33557250, 2021). "However, the iPSC model of MAPT p.R406W is uninformative with regards to PSEN1 mutations in AD or FTLD-TDP, further supporting its specificity for primary tauopathy." (PMID 30546007, 2018). "First, the presence of mutations in the genes encoding presenilin 1 (PS1), amyloid precursor protein (APP), and tau (MAPT) have been identified as causing familial AD (PS1M146V, APPSWE) or tauopathies including frontotemporal dementia and parkinsonism linked to chromosome 17 (MAPTP301L)." (PMID 28774322, 2017).
Ataxia (9 papers, 2017 to 2025). Ataxia refers to impaired coordination of voluntary muscle movement. "This cerebellar pathology in early-onset AD is further accompanied by cerebellar motor phenomena such as ataxia, especially in PSEN1 mutations." (PMID 33240072, 2020). "Early onset AD, especially from presenilin 1 mutations, exhibits cerebellar motor phenomena such as ataxia, as well as myoclonus or extrapyramidal symptoms." (PMID 32206613, 2020). "Despite almost all these symptoms having been reported in sporadic AD, extrapyramidal signs, behavioral, and psychiatric symptoms (anxiety, hallucinations, delusions) and ataxia are significantly more frequently found in EOFAD with PSEN1 mutations." (PMID 32767553, 2020). "Another patient carrying the PSEN1 p.Gly417Ala substitution also exhibited an atypical presentation: Cerebellar ataxia and extra pyramidal with pessimism syndrome." (PMID 31557888, 2019). "Another patient carrying the PSEN1 p.(Gly378Glu) substitution also exhibited an atypical presentation: cerebellar ataxia and extra pyramidal syndrome." (PMID 28350801, 2017). "Mutations in the gene encoding presenilin-1 (PS1) are found in the vast majority of cases of familial Alzheimer’s disease (FAD), with some of these patients presenting cerebellar damage with amyloid plaques and ataxia with unclear pathophysiology." (PMID 38289789, 2024).
depression (9 papers, 2010 to 2026). "Subjects with sporadic AD (n = 18), carriers of the A431E variant in PSEN1 (n = 7), people with depression (n = 6) and healthy controls (n = 17)." (PMID 35959289, 2022). "The other eight cases with late-onset dementia and three cases with a long history of depression have been reported in the family pedigree, underlying the high phenotype variability of PSEN1 mutations." (PMID 34207526, 2021). "This study describes a five-generation family, with a prevalent late-onset of the disease and a high frequency of depression, in which a new missense mutation (c.789T > G, p.Cys263Trp) in exon 8 of the PSEN1 gene was found." (PMID 34207526, 2021). "We measured Aβ isoform concentrations in CSF from 18 patients with SAD, 7 carriers of the FAD-associated presenilin 1 (PSEN1) A431E mutation, 17 healthy controls and 6 patients with depression using immunoprecipitation-mass spectrometry." (PMID 20145736, 2010). "The present study showed that multiple pontine genes, including Anxa1, Serpinf1, Arrb1, Cplx2, Nrg1, and Psen1 were altered in a model of depression." (PMID 39135796, 2024). "This study showed that SNS could downregulate the expression of Nrg1 and Psen1, indicating an improvement in depression, which is consistent with the results of previous studies." (PMID 39135796, 2024). "Of which, PSEN1 may contribute to depression-induced LUAD progression." (PMID 41694355, 2026). "Thus, early olfactory deficits could lead to the identification of depression patients with high risk of developing AD, as also occurs in our APP/PSEN1-Tg animals by showing early depression-like behaviour with later hyposmia traits." (PMID 33795014, 2021). "In the depression portrait, PSEN2 is downregulate while PSEN1 is upregulated." (PMID 33589676, 2021).
Myoclonus (9 papers, 2014 to 2024). Very brief, involuntary random muscular contractions occurring at rest, in response to sensory stimuli, or accompanying voluntary movements. "Nevertheless, the risk of myoclonus with lamotrigine may need to be considered, as it can theoretically exacerbate the myoclonus observed in some AD patients, especially those with PSEN1 mutations, even if the risk in generalized epilepsy is relatively low." (PMID 33297460, 2020). "In Alzheimer’s disease, myoclonus may be an early feature in presenilin 1 mutation carriers and a frequent late feature in sporadic disease." (PMID 28805718, 2017). "In addition to cognitive symptoms, EOFAD with PSEN1 mutations may present with some unusual clinical features, in particular myoclonus and seizures." (PMID 32767553, 2020). "PSEN1 mutation carriers are prone to present with atypical cognitive symptoms of behavioral change, language impairment, dyscalculia or executive impairment, and other neurological features of myoclonus, seizures, and pyramidal, extrapyramidal or cerebellar signs." (PMID 30090657, 2018). "Almost 30 presenilin 1 mutations, but not presenilin 2 or APP mutations, have been associated with the emergence of myoclonus." (PMID 28805718, 2017).
Spastic paraplegia (8 papers, 2022 to 2025). Complete loss of the ability to move the lower limbs accompanied by spasticity of the lower limbs. "Here, we describe the phenotype, imaging, ophthalmological and neuropathological features of a family with onset of progressive debilitating spastic paraplegia at age 23 due to a novel mutation in the PSEN1 gene." (PMID 36895955, 2023). "It is interesting to note that the gene for ALDH18A1 (Delta-1-Pyrroline-5-Carboxylate Synthase), a condition with symptoms comparable to those of people with PSEN1(A431E) mutation, is associated with spastic paraplegias (SPG9A and SP9B)." (PMID 37628788, 2023).
Stroke (8 papers, 2018 to 2025). Sudden impairment of blood flow to a part of the brain due to occlusion or rupture of an artery to the brain. "Studies have shown that Staufen protein levels are markedly upregulated in multiple cell and animal models of human neurodegenerative diseases, including those associated with mutations in presenilin 1, and microtubule-associated protein tau, as well as in stroke and myotonic dystrophy." (PMID 33024434, 2020). "The pathogenesis of VaD is complex and is the result of a variety of cardiovascular or genetic risk factors associated with Apolipoprotein E (APOE), angiotensin I converting enzyme (ACE), paraoxonase 1 (PON1), or presenilin 1 (PSEN1) genes, or due to stroke." (PMID 34938197, 2021). "A recent study also revealed that Presenilin 1-based Notch 1 signaling may control the generation, proliferation, and self-renewal of Rad-PCs isolated from the cortical peri-infarct areas after stroke." (PMID 37082656, 2023). "In this work, we showed that photothrombotic stroke caused an increase in the level of γ-secretase protein subunits of presenilin-1 and nicastrin in astrocytes, but not in penumbra neurons." (PMID 36289917, 2022). "Despite a family history of stroke in this patient, genetic studies did not reveal any pathogenic mutations in the APP, PSEN1 or PSEN2 genes." (PMID 29450646, 2018).
breast carcinoma (7 papers, 2013 to 2025). "Somatic PSEN1 mutations (such as Ala246Val, Glu71Lys and Arg269Cys) appeared in six major forms of cancer, including breast carcinoma, non-small cell lung cancer, colorectal adenocarcinoma, glioblastoma, endometrial carcinoma and ovarian tumors." (PMID 37176125, 2023). "It was also shown that increased expression of PSEN1 was associated with good disease-free survival in patients with breast cancer 62, suggesting that PSEN1 might play a role in inhibiting the formation and progression of some tumors." (PMID 37928268, 2023). "For instance, it has been found that PSEN1 overexpression reverses multi-chemoresistance in breast cancer by DNA initiating the damage response pathway; conversely, PSEN1 expression was notably elevated in patients diagnosed with gastric cancer." (PMID 40137900, 2025). "PIK3R5 gene has predictive potential for lymph node metastasis in breast cancer, while PSEN1 downregulation promotes the chemoradiotherapy resistance of esophageal carcinoma." (PMID 35480305, 2022). "Orzechowska and his colleagues found that overexpression of PSEN1 was beneficial to improving the disease-free survival of intraluminal breast cancer, while low expression of PSEN1 was instrumental in the disease-free survival of triple-negative breast cancer." (PMID 34568005, 2021). "The study also evaluated the influence of the ADAM10, NOTCH1, NOTCH3, HES1, LFNG and PSEN1 genes on breast cancer recurrence." (PMID 27888801, 2017).
amyotrophic lateral sclerosis (6 papers, 2020 to 2025). Amyotrophic lateral sclerosis (ALS) is a neurodegenerative disease characterized by progressive muscular paralysis reflecting degeneration of motor neurons in the primary motor cortex, corticospinal tracts, brainstem and spinal cord. "In a targeted sequencing analysis of 169 genes among 242 individuals of Caucasian descent in the United States, two presenilin mutations (PSEN1 W203C and PSEN1 I249L) were identified in individuals with amyotrophic lateral sclerosis (ALS)." (PMID 38339035, 2024). "Among these four variants, PSEN1 p.R269H and TARDBP p.G287S had been previously reported as causes of AD and amyotrophic lateral sclerosis (ALS), respectively, while the remaining two variants in the APP and PSEN2 genes were novel." (PMID 40813364, 2025).
dementia with Lewy bodies (6 papers, 2020 to 2025). "Missense mutations in the synuclein gene and presenilin 1 and 2 underscore the importance of delineating nosological entities within the Lewy body disease spectrum, considering concurrent biomarkers, imaging, and genetic data." (PMID 39682713, 2024). "Interestingly, PSEN2 Thr421 could have homology with PSEN1 Thr440, as PSEN1 T440del mutations were reported from patients with AD or dementia with Lewy bodies." (PMID 36362122, 2022).
early-onset Alzheimers disease (6 papers, 2017 to 2023). A rare form of Alzheimer's disease, occurring before the age of 65. "Familial early-onset Alzheimer’s disease (FEOAD) or early-onset AD (EOAD) associated with dominant mutations in APP, PSEN1 and PSEN2 have a high penetrance for displaying many of the clinical symptoms associated with AD." (PMID 36834781, 2023).
gastric cancer (6 papers, 2016 to 2025). A primary or metastatic malignant neoplasm involving the stomach. "Earlier studies denoted that miR-193a downregulates the PSEN1 level to constrain cell proliferation and invasion of gastric cancer, which was in accord with our results." (PMID 35096015, 2021). "All the results indicated that miR-193a regulated the expression of PSEN1 in gastric cancer cells HGC-27." (PMID 34335753, 2021). "The result that PSEN1 fosters cancer cell EMT was also confirmed in gastric cancer and lung adenocarcinoma." (PMID 35096015, 2021). "The newly identified miR-193a/PSEN1 axis provides novel insight into the pathogenesis of gastric cancer." (PMID 34335753, 2021). "The expression of PSEN1 was evaluated by RT-qPCR and we found that it was downregulated in peritumoral normal tissues compared to that in gastric cancer tissues (P < 0.05)." (PMID 34335753, 2021). "PSEN1 hastens gastric cancer invasion and metastasis, which may be a possible biomarker and therapeutic target." (PMID 35096015, 2021). "The shortcoming of our study is that it has not further explored the mechanism of the miRNA/PSEN1/PI3K/Akt axis in gastric cancer." (PMID 34335753, 2021).
ischemia (6 papers, 2020 to 2022). A hypoperfusion of the BLOOD through an organ or tissue caused by a PATHOLOGIC CONSTRICTION or obstruction of its BLOOD VESSELS, or an absence of BLOOD CIRCULATION. "Three days post-ischemia, the highest level of presenilin 1 (PSEN1) mRNA was noted in the neurons of CA3 region of the hippocampus." (PMID 35741821, 2022). "In the CA1 area of the hippocampus, the expression of presenilin 1 and 2 genes increased within 2–7 days after ischemia." (PMID 33679381, 2021). "The cortex exhibited an increase of presenilin 1 and 2 mRNAs within 1–8 days after local ischemia with recirculation, whereas, the hippocampus exhibited upregulation of presenilin 1 and 2 mRNAs within 4–8 days after ischemia." (PMID 33679381, 2021). "Alterations in the mean expression level of presenilin 1 gene are statistically significant between 2 and 30 and between 7 and 30 days following ischemia." (PMID 33671097, 2021). "In the CA3 subfield, the expression of the presenilin 1 gene increased in 2–7 days following ischemia." (PMID 33679381, 2021). "Expression of the presenilin 1 gene was significantly elevated above the control values 2–7 days after ischemia and decreased below the control values at day 30 of recirculation." (PMID 31713815, 2020). "In total, upregulation of genes found in our study suggests that β-secretase (after 30 days), presenilin 1 (after 2–7 days) and 2 (after 30 days) are activated at different times after ischemia in the CA3 region of the hippocampus." (PMID 31713815, 2020). "In the CA1 area, the expression of presenilin 1 and 2 genes increased during 2–7 days after ischemia." (PMID 32366028, 2020). "Seven days post-ischemia, the expression of the presenilin 1 gene was reduced and the presenilin 2 gene was increased." (PMID 32366028, 2020).
Obesity (6 papers, 2016 to 2025). Accumulation of substantial excess body fat. "Amyloid precursor protein/presenilin-1 (APP/PS1) transgenic mice fed with a cholate, cholesterol, and high-fat diet is reported to induce NAFLD without hyperglycemia and obesity." (PMID 36143853, 2022).
prion disease (6 papers, 2009 to 2025). A transmissible disease that is caused by a protein that is able to induce abnormal folding of normal cellular proteins, leading to characteristic spongiform brain changes, which are associated with neuronal loss without an inflammatory response. "Among genes associated with prion diseases, the over-expression of some (PSEN1, FYN, SMC3, CHD2, EP300) in late-cycle could be rationalized by considering related proteins in humans, which, when expressed in their monomeric (soluble) form, exert protective functions for cellular homeostasis." (PMID 37048113, 2023).